CPA4 (carboxypeptidase A4)
Description:
Metalloprotease that cleaves hydrophobic C-terminal residues with a preference for -Phe, -Leu, -Ile, -Met, -Tyr and -Val. May function in peptide hormone and/or neuropeptide catabolism.
Synonyms: CPA3
Tractability: Small molecule: a structure with a bound ligand is known; a high-quality ligand is known. Antibody: UniProt places it where antibodies can reach, with high confidence; UniProt predicts a signal peptide or a membrane-spanning region; its Gene Ontology location is reachable by antibodies, with medium confidence; the Human Protein Atlas places it where antibodies can reach. PROTAC: a small molecule that binds it is known.
Target class: Metallo protease; Metallo protease MC clan; Protease; Metallo protease M14A subfamily; Enzyme
Gene: Protein-coding gene on chromosome 7 (130,293,134 to 130,324,180, forward strand). Ensembl gene ENSG00000128510.
Subcellular location: Secreted
Subcellular location (Human Protein Atlas): Nucleoplasm; Plasma membrane; Centriolar satellite; Predicted to be secreted
Gene Ontology:
Molecular function: metallocarboxypeptidase activity; zinc ion binding
Biological process: hormone catabolic process; peptide catabolic process; proteolysis
Cellular component: extracellular region
Genetic constraint (gnomAD): Loss-of-function variants: 26 observed, 32.96 expected, observed/expected ratio (o/e) 0.79, 90% interval 0.58 to 1.09. The upper end of that interval is the gene's LOEUF score, 1.09, which puts it in group 4 of 6, group 1 being the genes least tolerant of losing a copy. Missense variants: 318 observed, 380.96 expected, observed/expected ratio (o/e) 0.83, 90% interval 0.76 to 0.92. Synonymous variants: 160 observed, 158.88 expected, observed/expected ratio (o/e) 1.01, 90% interval 0.88 to 1.15.
Homologues: Orthologues: chimpanzee CPA4 (99% identical), macaque CPA4 (94% identical), dog CPA4 (89% identical), pig CPA4 (88% identical), rabbit CPA4 (86% identical), mouse Cpa4 (84% identical), guinea pig CPA4 (82% identical), Caenorhabditis elegans T06A4.1 (38% identical), Caenorhabditis elegans Y47G6A.19 (37% identical), Drosophila melanogaster CG3108 (35% identical), Caenorhabditis elegans Y59C2A.1 (34% identical), Drosophila melanogaster CG8563 (34% identical), and 16 more. Paralogues in human: CPA2 (63% identical), CPA1 (54% identical), CPA5 (50% identical), CPB1 (41% identical), CPA6 (39% identical), CPA3 (37% identical), CPB2 (35% identical), CPO (30% identical).
Diseases named in the same sentence as CPA4 in open-access papers:
CPA4 is named in the same sentence as 34 diseases in open-access papers, as found by Europe PMC text mining. Sharing a sentence is not in itself a finding about the gene and the disease. The quoted sentences say what the papers report.
breast carcinoma (12 papers, 2019 to 2025). "Next, it was worthwhile to test the levels of CPA4 in breast cancer serum samples, and studied its diagnostic efficacy or prognosis value in TNBC." (PMID 33746592, 2021). "Accordingly, we conducted a first study to investigate the diagnostic and prognostic significance of CPA4 in the case of breast cancer (BC), the most common form of malignancy in women." (PMID 30875843, 2019). "In this study, we aimed to investigate the diagnostic and/or prognostic value of serum CPA4 levels in breast cancer." (PMID 30875843, 2019). "Similarly, in breast cancer, a study found that high CPA4 expression was significantly associated with aggressive phenotypes in TNBC." (PMID 40805261, 2025). "Furthermore, high levels of CPA4 mRNA were significantly associated with unfavourable overall survival OS in breast cancer patients." (PMID 33746592, 2021). "CPA4 can also function as the diagnostic and prognostic marker in human breast cancer." (PMID 32347291, 2020). "More studies are required to fully elucidate the impact of CPA4 expression and, importantly, the potential benefits of CPA4 inhibition on breast cancer prognosis and treatment response." (PMID 40805261, 2025). "Estrogen Signaling: CPA4’s involvement in estrogenic signaling is particularly important in hormone-responsive cancers such as endometrial and breast cancers." (PMID 40805261, 2025). "This discrepancy highlights the complexity of CPA4’s role in breast cancer and underscores the need for further investigation." (PMID 40805261, 2025). "For example, a recent study showed that CPA4 promotes tumour cell proliferation in breast cancer by affecting the ANG1‐CPA4 axis." (PMID 38494845, 2024). "The serum and mRNA expression levels of CPA4 were also found to be prognostic biomarkers for breast cancer patients." (PMID 35686102, 2022). "The role of CPA4 in breast cancer cell self-renewal ability was determined using the mammosphere formation in serum-free suspension culture." (PMID 33746592, 2021). "In future studies, we will further identify the molecular mechanisms of CPA4 in breast cancer progression." (PMID 33746592, 2021). "In Kaplan-Meier survival analysis, either high CPA4 or ALDH1A1 levels was significantly correlated with poor survival in breast cancer patients." (PMID 33746592, 2021). "Kaplan-Meier survival analysis showed that breast cancer patients with high levels of ALDH1A1 or CPA4 were significantly correlated with poor overall survival." (PMID 33746592, 2021). "Previous studies have reported the critical involvement of CPA4 in non-small lung cancer, breast cancer, hepatocellular carcinoma, and gastric cancer." (PMID 32347291, 2020). "Cpa4 expression is also useful for diagnosing breast cancer." (PMID 40076501, 2025).
breast carcinoma (continued). "CPA4 is a Zn‐containing metallocarboxypeptidase localized on chromosome 7q32 and has been found to promote the proliferation and migration of tumour cells in a variety of cancers, including breast cancer and colon cancer." (PMID 38494845, 2024). "Previous trials suggested that the inhibition of CPA4 could reduce the number of breast cancer cells with stemness properties and may be a potential target for TNBC therapy." (PMID 34827136, 2021). "We examined the effects of CPA4 knockdown on breast cancer proliferation via MTS assay." (PMID 33746592, 2021). "Furthermore, CPA4 was demonstrated to be a functional gene and may promote breast cancer progression." (PMID 33746592, 2021). "Breast Cancer: In breast cancer (BC), studies have shown that MCF-7 cells, a common hormone receptor-positive BC cell line, tend to secrete more CPA4 compared to human mammary epithelial cells (HMEpC)." (PMID 40805261, 2025). "Kaplan-Meier survival analysis showed that CPA4 and ALDH1A1 over-expression was significantly correlated with overall survival of breast cancer patients." (PMID 33746592, 2021). "Immunohistochemistrical analysis demonstrated that CPA4 was highly expressed in 32.1% of breast cancer samples (45/140), but weak or no staining of CPA4 occurred in the adjacent normal tissues." (PMID 33746592, 2021). "We conclude that CPA4 is prognostically and diagnostically not futile in breast cancer, when used in combination with the other considerations and measurements." (PMID 30875843, 2019). "We conclude that CPA4 is diagnostically and prognostically not futile when used in combination with the other considerations and measurements in breast cancer." (PMID 30875843, 2019). "In clinical breast cancer samples, site analysis showed that CPA4 expression in TNBC was higher than that in non-TNBC, and there was a positive correlation between CPA4 and ANG1 in breast cancer." (PMID 37162264, 2023). "Interestingly, a unique O-glycosylation pattern of CPA4 was observed in MCF-7 cell media but was absent in HMEpC media, further suggesting a potential role for CPA4 in breast cancer development." (PMID 40805261, 2025).
pancreatic cancer (11 papers, 2016 to 2025). "PI3K-AKT-mTOR Signaling: Overexpression of CPA4 in pancreatic cancer cells has been shown to activate the PI3K-AKT-mTOR pathway, promoting EMT, enhancing cell proliferation, and increasing drug resistance." (PMID 40805261, 2025). "Pancreatic Cancer (PC): In PCs, Sun and colleagues demonstrated that the overexpression of CPA4 in PC tissues had a significant correlation with tumor progression." (PMID 40805261, 2025). "Both the CPA4 and TACSTD2 proteins are overexpressed in pancreatic carcinoma in humans and are associated with decreased survival." (PMID 35169238, 2022). "As such, pVHL and CPA4 are the most and the least sensitive IHC biomarkers respectively for pancreatic cancer diagnosis." (PMID 34988027, 2021). "CPA4 is imprinted and may be a strong candidate gene for the aggressiveness of prostate cancer as well as a promising diagnostic serum biomarker for both pancreatic cancer and non-small cell lung cancer and an adverse prognostic marker for gastric cancer, NSCLC, and colorectal cancer." (PMID 31552180, 2019). "Recent studies in our lab also indicated that CPA4 level was significantly elevated in pancreatic cancer tissues as well as serum samples, and was closely correlated with tumor progression." (PMID 27780921, 2016). "CPA4 has been previously reported to promote epithelial-mesenchymal transition in pancreatic cancer, cardiomyocyte hypertrophy and the growth of non-small cell lung cancer through positive regulation of the AKT signalling pathway, and it is closely related to the development of a variety of cancers." (PMID 38049405, 2023). "The current review study identifies 22 IHC biomarkers as diagnostic tools for pancreatic cancer that embrace: Pentraxin-3, ENO1, REG4, POSTN, CA125, CA242, Galectin-1, Galectin-9, Maspin, pVHL, MUC1, MUC5AC, THBS2, LTBP2, CPA4, IMP3, CD13, Dkk1, KOC, S100P, Mesothelin, PAM4." (PMID 34988027, 2021). "Previous studies in our lab indicated that CPA4 level was significantly elevated in pancreatic cancer tissues as well as serum samples, and it might be a potential diagnostic serum marker for pancreatic cancer." (PMID 27780921, 2016).
prostate carcinoma (10 papers, 2009 to 2025). A carcinoma that arises from epithelial cells of the prostate gland. "A specific CPA4 SNP was found to be associated with an increased risk of aggressive prostate cancer." (PMID 40805261, 2025). "CPA4 is located in the imprinted domain on 7q32 and is associated with aggressiveness of the prostate cancer and the poor prognosis of gastric cancer patients." (PMID 36461044, 2022). "Previously studied showed that upregulated mRNA levels of CPA4 in androgen-independent prostate cancer cells is associated with the Histone Hyperacetylation signaling pathway." (PMID 34827136, 2021). "Among younger men the rs2171492 nonsynonymous coding SNP in CPA4 was associated with an increased risk of intermediate-risk and high-risk prostate cancer." (PMID 19245716, 2009). "Carboxypeptidase 4 (CPA4) is a zinc-dependent metallocarboxypeptidase on chromosome 7q32 in a region linked to prostate cancer aggressiveness." (PMID 19245716, 2009). "The nonsynonymous coding SNP (rs2171492, Cys303Gly) in CPA4 was associated with an increased risk of aggressive prostate cancer among younger patients (< 66 years)." (PMID 19245716, 2009). "Six CPA4 single-nucleotide polymorphisms were genotyped, and evaluated for their relation to prostate cancer." (PMID 19245716, 2009). "We examined the association between genetic variation in CPA4 and intermediate-to-high risk prostate cancer." (PMID 19245716, 2009). "When the analysis was applied the overall study population (all ages), we did not observe any statistically significant associations between CPA4 and prostate cancer." (PMID 19245716, 2009). "Our study suggests that the rs2171492 nonsynonymous coding SNP in CPA4 confers an increased risk of high risk prostate cancer among younger patients." (PMID 19245716, 2009). "This evaluation of genetic variants across CPA4 detected a positive association between the nonsynonymous coding SNP (Cys303Gly) rs2171492 and high risk prostate cancer among men with an earlier age of disease onset." (PMID 19245716, 2009). "The coding variation in CPA4 may confer an increased risk of intermediate-to-high risk prostate cancer among younger patients." (PMID 35686102, 2022). "Furthermore, it is reported that CPA4 is located on chromosome 7q32 in a region linked to prostate cancer aggressiveness, and Sun suggested that CPA4 is closely associated with colorectal cancer liver metastasis." (PMID 34827136, 2021). "Coding variation in CPA4 may confer increased risk of intermediate-to-high risk prostate cancer among younger patients." (PMID 19245716, 2009). "CPA4 substrates like neurotensins, granins, and opioid peptides have been associated with increased cell growth, proliferation, and motility, which may lead to the aggressiveness of prostate cancers." (PMID 40805261, 2025). "It has been reported that latexin (LXN) can inhibit human CPA4, in which the expression is induced in prostate cancer cells after treatment with histone deacetylase inhibitors." (PMID 34827136, 2021). "Prostate Cancer: Several studies have demonstrated a link between CPA4 and prostate cancer." (PMID 40805261, 2025). "In prostate cancer, CPA4 gene was reported to be imprinted and may be closely associated with cancer aggressiveness." (PMID 27780921, 2016). "In the overall population (all ages) none of the CPA4 SNPs demonstrated a statistically significant association with prostate cancer." (PMID 19245716, 2009). "Within this 7q32 region is CPA4 (previously identified as CPA3), part of the carboxypeptidase gene family and a strong candidate for the putative prostate cancer aggressiveness gene." (PMID 19245716, 2009). "The results by Huang and colleagues demonstrated that treatment of prostate cancer cell lines PC3, DU145, and BH1 with sodium butyrate (NaBu), a histone deacetylase (HDAC) inhibitor, increased the expression of CPA4 mRNA in a p21 WAF1/CIP1 transactivation-dependent manner." (PMID 40805261, 2025).
prostate carcinoma (continued). "CPA4 was first discovered in prostate cancer cells, but it is now known to be expressed in various tissues throughout the body." (PMID 40805261, 2025).
gastric cancer (8 papers, 2019 to 2025). A primary or metastatic malignant neoplasm involving the stomach. "Further analysis showed that the elevated expression of CPA4 in gastric cancers was significantly associated with tumor size, stage, lymph node metastasis, depth of invasion and distant metastasis, suggesting its use as a biomarker for the prognosis of the disease." (PMID 40805261, 2025). "Some studies revealed that CPA4 is connected with various cancer cells in its differentiation and growth, including non-small-cell lung cancer and gastric cancer." (PMID 34827136, 2021).
non-small cell lung carcinoma (8 papers, 2019 to 2025). A group of at least three distinct histological types of lung cancer, including non-small cell squamous cell carcinoma, adenocarcinoma, and large cell carcinoma. "Moreover, the serum levels of CPA4 were higher in non-small cell lung cancer (NSCLC) patients (n = 100) than healthy controls (n = 80)." (PMID 40805261, 2025). "A paper from Yan suggested that the inhibition of CPA4 might be of great significance for improving early stage non-small cell lung cancer survival after ablation." (PMID 34827136, 2021). "The following studies found an excessive expression of CPA4 in soft tissue and non-small-cell lung cancers and reported that it could be used as an early sign of poor prognosis." (PMID 30875843, 2019). "In the setting of non-small cell lung cancer (NSCLC), circ-CPA4 and circPIP5K1A have been identified as key regulators of cancer cell behavior and immune evasion." (PMID 39915884, 2025). "For instance, circIGF2BP3, circFGFR1 and circ-CPA4 could promote immune evasion and inhibit CD8+ T cell response in non-small cell lung cancer by facilitating the PD-L1 expression." (PMID 36747239, 2023). "However, in patients with non-small-cell lung cancer, it has also been recommended that the CYFRA21-1 levels should be considered besides the CPA4 levels." (PMID 30875843, 2019).